HTRA2 (HtrA serine peptidase 2)
Diseases named in the same sentence as HTRA2 in open-access papers (continued):
Sharing a sentence is not in itself a finding about the gene and the disease.
myocardial ischemia (1 paper, 2021). A disorder of cardiac function caused by insufficient blood flow to the muscle tissue of the heart. "Furthermore, HtrA2 may be a potential biomarker for the identification of ischemia/reperfusion injury because the levels of Htra2 in blood serum are significantly increased in mice with myocardial ischemia/reperfusion injury and also in human patients with ST-segment elevation myocardial infarction." (PMID 33937324, 2021).
progeria (1 paper, 2018). "Previously, a variety of studies have discovered that mice lacking Omi/HtrA2 exhibited symptoms of progeria and premature senescence, which was associated with deficiencies in autophagy." (PMID 30574416, 2018).
retinal degeneration (1 paper, 2020). Degeneration of the retina. "Because HtrA2/Omi specifically degraded oligomeric α-Syn, co-expression of HtrA2/Omi and α-Syn in Drosophila eye maintained a healthy retina, while the expression of α-Syn induced retinal degeneration." (PMID 32210343, 2020).
synovitis (1 paper, 2023). Inflammation of a synovial membrane. "When participants were separated into two groups based on the presence of active synovitis (GSUS ≥2 or PDUS ≥1), HtrA2 levels were considerably higher in patients with active synovitis compared with those with inactive synovitis." (PMID 37287073, 2023). "Interestingly, HtrA2 levels in the SF of RA patients were elevated in proportion to synovitis severity and correlated with the expression of proinflammation cytokines and chemokines, such as IL-6, IL-8, and CCL2." (PMID 37287073, 2023).
tauopathy (1 paper, 2025). Neurodegenerative disorders involving deposition of abnormal tau protein isoforms (tau proteins) in neurons and glial cells in the brain. "Moreover, we found that HTRA2 expression decreased in the brains of tauopathy patients and tauopathy model mice, whereas HTRA2 overexpression in neurons partially attenuated memory and synaptic plasticity deficits in the PS19 tauopathy model mice." (PMID 39794315, 2025). "We found that PP2B-Aα protein levels were decreased in PS19 mice and reversed upon HTRA2 overexpression, implicating that HTRA2 overexpression partially attenuates synaptic plasticity impairment, cognitive deficits, and pathologies of tauopathy model mice possibly by affecting the PP2B phosphatase." (PMID 39794315, 2025). "Moreover, we demonstrate the effectiveness of this strategy through showing that an identified protein, HTRA2 can regulate synaptic plasticity and learning and memory in both WT and tauopathy model mice." (PMID 39794315, 2025). "We further explored whether HTRA2 expression was altered in AD and related tauopathies." (PMID 39794315, 2025). "Therefore, we studied the effect of HTRA2 overexpression on synaptic plasticity and cognitive behaviors in the PS19 tauopathy model mice." (PMID 39794315, 2025). "Moreover, we found that HTRA2 protein levels decreased in the hippocampal tissue samples of rTG4510 and PS19 mice, two animal models of tauopathy." (PMID 39794315, 2025). "On the other hand, we found that HTRA2 expression was decreased in the brains of AD and FLTD-U patients and different tauopathy model mice but not altered in the brain of 5×FAD mice." (PMID 39794315, 2025).
cancer (20 papers, 2013 to 2025). A tumor composed of atypical neoplastic, often pleomorphic cells that invade other tissues. "While the involvement of HtrA1 in cancer is quite prevalent, there have been only a few direct reports of HtrA2’s association with oncogenesis." (PMID 35187085, 2022). "Association of HtrA2 with cancer and neurodegenerative disorders makes it a promising therapeutic target." (PMID 23457469, 2013). "Furthermore, Omi/HtrA2 expression and function is associated with autophagy and mitophagy in Parkinson’s and Huntington’s disease, and it is known to be upregulated in a variety of cancers." (PMID 26784188, 2016). "HTRA2 exhibits dual roles in cancer development—while it promotes apoptosis and has tumor-suppressive potential, its dysregulation or reduced expression is also associated with tumor cell survival and resistance." (PMID 40722819, 2025). "Not only so, HtrA2 tends to express mainly at CD8 T, DC, plasma, fibroblasts, mast, and malignant cell clusters, possibly indicating that HtrA2 also functions in immune cells or stromal cells other than cancer cells." (PMID 36704205, 2023). "Based on the UALCAN database, we found that promoter regions of HtrA2 were shown to be significantly less methylated in tumor tissues of HCC than in the normal tissues adjacent to cancer (P < 0.001)." (PMID 36704205, 2023). "The expression of HtrA2 changes in oncogenesis and is upregulated or downregulated in tumor cells depending on the type of cancer." (PMID 36982965, 2023). "To explore such pathways, we compared the proteomic signature of irradiated senescent cancer cells treated with the HtrA2 inhibitor Ucf‐1 to untreated cells by mass spectrometry." (PMID 35122388, 2022). "This suggests that HtrA2's function in radiation‐induced senescence can be extended to other cancer cell lines." (PMID 35122388, 2022). "Biopsy sample analyses of specific cancers exhibited altered expression of HtrA2 suggesting its role in those cancers." (PMID 35187085, 2022). "These unique features along with its multitasking potential make HtrA2 a promising therapeutic target both in cancer and neurodegeneration." (PMID 35187085, 2022). "HtrA2 has been found to be widely expressed in several cancer cell lines where over-expression triggered cell death." (PMID 35187085, 2022). "HTRA2 is also widely detected in many cancers; however, its regulation is variable depending on the type of tumour." (PMID 34639128, 2021). "It is reported that both HtrA2 mRNA and protein are significantly elevated in epithelial ovarian carcinoma in correlation to the stage of cancer progression." (PMID 34639128, 2021). "Further investigations are required to clarify the involvement of HtrA2 in different cancers and its potential use as a therapeutic target." (PMID 34639128, 2021). "The expression level of HTRA2 mRNA in different types of cancer tissues indicated that the expression level of HTRA2 in GC tissues was also higher than that in control group." (PMID 34708890, 2021). "In this study, we demonstrated that GSDME augments the intrinsic apoptotic pathway in cancer cells by forming pores in the mitochondria and releasing critical proapoptotic factors such as Cyt c and HtrA2." (PMID 30976076, 2019). "HtrA2, a trimeric proapoptotic serine protease is involved in several diseases including cancer and neurodegenerative disorders." (PMID 23457469, 2013). "However, the role of HtrA2 is not fully understood, since an increased or decreased expression of HtrA2 was reported in different cancers." (PMID 37445598, 2023). "While the importance of CCL2/CCR2 signaling in macrophages during cancer progression is well documented, HtrA2 may regulate macrophage recruitment." (PMID 36704205, 2023).
cancer (continued). "Actually, an emerging chemotherapy-resistance mechanism, driven by WT1 downregulation, due to transcript cleavage via HTRA2, a protease overexpressed under cytotoxic therapy, has been shown to increase cancer cell survival, based on C-MYC/JUNB upregulation, which is normally repressed by WT1." (PMID 35453662, 2022). "Htra2, a mitochondrial serine protease that is a known regulator of apoptosis, was identified through an siRNA screen as a positive mediator of radiation‐induced senescence in cancer cells." (PMID 35122388, 2022). "Moreover, a decrease in HTRA1 and HTRA2 transcripts’ levels in cancers with a high level of microsatellite instability compared to microsatellite stable ones has been observed." (PMID 32486357, 2020). "A low level of HtrA1 or/and HtrA2 in cancer tissue correlated with poorer patient survival." (PMID 32486357, 2020). "HtrA2(Omi), belonging to the high-temperature requirement A (HtrA) family of stress proteins, is involved in the maintenance of mitochondrial homeostasis and in the stimulation of apoptosis, as well as in cancer and neurodegenerative disorders." (PMID 22851136, 2013). "Consequently, HTRA2 is often found to be downregulated during cancer development." (PMID 40722819, 2025). "However, HtrA2 is reported to be downregulated in other cancers." (PMID 34639128, 2021). "Similarly to HtrA1 and HtrA2, HtrA3 exhibits proapoptotic function in certain pathological conditions; upon action of chemotherapeutic drugs, the mitochondria-localized HtrA3 is released into the cytosol and it participates in the stimulation of mitochondria-mediated apoptosis of cancer cells." (PMID 32486357, 2020). "For example, overexpression of HtrA2 substrates such as IAPs and the Wilms’s tumor suppressor protein WT1 in several cancers suggests modulation of HtrA2 protease activity can effectively regulate their relative levels in the cells." (PMID 23457469, 2013). "Besides their involvement in neurodegenerative diseases, both HtrA2 and CHOP as an ISR component were found to be involved in cancer." (PMID 36982965, 2023). "Interestingly, GSDME, in turn, enable us to enhance the intrinsic apoptotic pathway in cancer cells by forming pores in the mitochondria with GSDME-N and liberating proapoptotic factors (including Cyt c and HtrA2)." (PMID 36457716, 2022). "Finally, to show the relevance of HtrA2 as a regulator of senescence in another cancer cell line, HCT116 cells were treated with an inhibitor of HtrA2 catalytic activity, Ucf‐101, and irradiated." (PMID 35122388, 2022). "Like HtrA2, HTRA3 expression is variable in cancer depending on the tumour type." (PMID 34639128, 2021). "Proteases such as ubiquitin specific peptidase 30 (USP30), presenilin associated rhomboid like (PARL), and HtrA serine peptidase 2 (HTRA2) in the UPRmt can interact with mitophagic regulator PINK1-Parkin, and then inhibit mitophagy and maintain mitochondrial proteostasis in cancers." (PMID 30577555, 2018). "The proteases HtrA2 and OMA1 might be new targets in cancer therapy; however, at the moment, no studies with specific modulators of these enzymes are available." (PMID 37445598, 2023).
tumor (18 papers, 2004 to 2025). "In the present study, HtrA2 was found to have high expression in HCC tumor tissue, and its high expression was associated with hypomethylation." (PMID 36704205, 2023). "This may indicate a compensatory response of tumor cells to the reduced levels of proteins encoded by these genes as a result of the proteolytic action of HTRA2." (PMID 41465443, 2025). "Therefore, HtrA2 has the potential to be a diagnostic marker for multiple tumor types, including HCC." (PMID 36704205, 2023). "Furthermore, the infiltration of most immune cells is significantly associated with HtrA2 expression, suggesting a possible involvement of HtrA2 in regulating the tumor immune response." (PMID 36704205, 2023). "In the TCGA-HCC cohort, the mRNA expression of HtrA2 in tumor tissue was compared with that in normal or paired adjacent tissues." (PMID 36704205, 2023). "Using the TCGA sequencing data, an analysis of HtrA2 mRNA expression in multiple human tumor tissues was performed." (PMID 36704205, 2023). "Since HtrA2 can regulate tumor cell apoptosis, there is a possible connection between miR-519E and HtrA2." (PMID 36704205, 2023). "To confirm HTRA2 was derived from GC tumor, we further detected in primary cancerous and neighboring noncancerous tissues from GC cases." (PMID 34708890, 2021). "One candidate tumor‐related mRNA named HTRA2 was then evaluated in GC samples with quantitative real‐time polymerase chain reaction (qRT‐PCR)." (PMID 34708890, 2021). "HtrA2 is also reported to be reduced in malignant breast tumours with increasing tumour stage and severity." (PMID 34639128, 2021). "Here, we reported tumor‐related HTRA2 mRNA's expressing state in the plasma of cases with GC and healthy ones, and its level was much higher in the serum of GC." (PMID 34708890, 2021). "The levels of HtrA1 and HtrA2 proteins were reduced in tumor tissue when compared to unchanged mucosa, specifically in primary lesions of metastasizing disease." (PMID 32486357, 2020). "The expression of HTRA2 changes during neoplastic transformation; however, it is down-regulated in some tumors and upregulated in others, which suggests that the HTRA2 expression varies depending on tumor type." (PMID 32486357, 2020). "The results implied that the tumor apoptosis was induced by the upregulated expression of HtrA2, caspase 6, caspase 7, caspase 10, Gas2, and Lamin A." (PMID 27275821, 2016). "We next analyzed the effect of cytotoxic drugs on HtrA2-mediated cleavage of WT1 in the tumor-derived cell lines U2OS and H1299, which both express endogenous WT1." (PMID 20122399, 2010). "We show that endogenous WT1 in tumor cells is cleaved following cytotoxic drug treatment and demonstrate that this cleavage is HtrA2 dependent." (PMID 20122399, 2010). "The relationship between HtrA2 and miR-519E may be significant because HtrA2 regulates tumor cell apoptosis." (PMID 40699800, 2025). "Collectively, these in vivo results showed that Apoptin caused significant changes in the expression of AIF, HtrA2, Smac/Diablo, and Cyto‐C and that BAPTA‐AM could reduce the expression of Smac/Diablo and Cyto‐C in Apoptin‐treated tumor tissues." (PMID 36515089, 2023). "The results showed high HtrA2 expression (P < 0.001) presented in tumor tissues in TCGA-HCC." (PMID 36704205, 2023). "Additionally, HTRA2 expressing state decreases inside several tumors and increases inside other tumors, demonstrating that HTRA2 expressing state changes following tumor category." (PMID 34708890, 2021). "Candidate tumor‐related HTRA2 mRNA was then quantitated in GC tissues and plasmas, respectively." (PMID 34708890, 2021). "WT1 cofactors that block HtrA2-mediated processing of WT1 could potentially provide a switch that regulates the dichotomy of the tumor suppressor and oncogenic properties of WT1." (PMID 20122399, 2010). "Thus, ablation of HtrA2 in two different tumor cell lines by siRNA blocks the induction of WT1 cleavage by cytotoxic drugs." (PMID 20122399, 2010).
tumor (continued). "Thus, HTRA2 plays a critical role in maintaining apoptotic signaling balance and tumor suppression." (PMID 40722819, 2025). "Moreover, a role of HtrA2/Omi as a tumor suppressor in malignancies is discussed." (PMID 37594630, 2023). "Western‐blot analysis of tumor tissues showed that the expression levels of AIF, HtrA2, Smac/Diablo, and Cyto‐C in the Ad‐Vp3 + BAPTA‐AM and Ad‐Vp3 groups were significantly higher than the BAPTA‐AM, Ad‐Mock, and PBS groups (p < 0.05)." (PMID 36515089, 2023). "In the case of HtrA2, the protein was present in tumor cells, but not detected in stromal compartment, which is compatible with the intracellular location of the protease." (PMID 32486357, 2020). "Although investigations concerning the expression of Omi/HtrA2 in relation to tumour stage and grade are lacking, it is reasonable to assume that the disturbed balance between XIAP and Smac/DIABLO during progression of RCCs cannot be adjusted by Omi/HtrA2." (PMID 15328523, 2004). "However, studies on the correlation between HtrA2 and tumor immune infiltration are currently lacking." (PMID 36704205, 2023).
neurodegenerative disease (12 papers, 2014 to 2025). A disorder of the central nervous system characterized by gradual and progressive loss of neural tissue and neurologic function. "We further identified HtrA2, a mitochondrial protease that was previously linked to mitochondrial fitness and development of neurodegenerative diseases, as a new DELE1 protease that appeared to cleave preferentially DELE1 at a new site that we identified." (PMID 38555279, 2024). "HTRA2, a member of high-temperature requirement serine protease A family, has also been associated with neurodegenerative diseases." (PMID 35707770, 2022). "For example, HTRA2 has been linked to neurodegenerative diseases such as PD and AD." (PMID 39794315, 2025). "Here we present new data on HtrA2 and add further evidence that mitochondrial proteostasis is indeed of physiological and pathophysiological relevance for neurodegenerative diseases." (PMID 32385113, 2020). "Therefore, the specific modulation of the HTRA2 protease activity by specific peptide ligands could be a promising therapeutic strategy in neurodegenerative diseases." (PMID 34440217, 2021). "In the MM1 subtype, we found variants in genes involved in a heterogeneous group of molecular processes and neurodegenerative diseases, while in the VV2, we found an over-representation of genes involved in PD, such as HTRA2, PINK1, and PRKN." (PMID 36517866, 2022).
mitochondrial disease (4 papers, 2017 to 2023). "Regardless of its place in the pantheon of PD-associated proteins, HTRA2 is a mitochondrial protein whose genetic loss of function thus represents a mitochondrial disease." (PMID 30013019, 2018). "Uncertainties regarding the cytopathological roles of HTRA2 mutations may result from the complexities of mitochondrial disease." (PMID 30013019, 2018). "Antisense inhibition of htrA revealed that reduction of HTRA2 as suggested by the reduced mRNA levels of HTRA2, partially phenocopied D. discoideum mitochondrial disease models with aberrant multicellular development and reduced growth rates with no corresponding defect in endocytosis." (PMID 35159273, 2022).
infection (3 papers, 2008 to 2025). The state of being infected such as from the introduction of a foreign agent such as serum, vaccine, antigenic substance or organism. "A previous study implicated HtrA2 in cytomegalovirus-associated programmed cell death, a process occurring late in the infection (day 6–10 post-infection) and antagonized to some extent by the viral protein vMIA65." (PMID 29855523, 2018). "Baricitinib partially reversed pro-apoptotic changes, suppressing HIF-1a and cleaved Caspase-3, but further reduced Survivin and HTRA2, indicating selective modulation of apoptosis during infection." (PMID 41255708, 2025). "In vivo, we show that HtrA2 limits IL-18-dependent early inflammatory responses to MCMV (40 hours post-infection)." (PMID 29855523, 2018). "Blocking protein synthesis with cycloheximide at 18 hours post-infection revealed slower ASC oligomer turnover in HtrA2- or ATG5-depleted cells than in control cells." (PMID 29855523, 2018). "Levels of mature 36 kDa HtrA2/Omi levels were similar to uninfected cells at 24 h, but increased by 48 h and continued to accumulate over the course of infection." (PMID 18769594, 2008). "Here, we demonstrate the central role of HtrA2/Omi executing a serine protease-dependent pathway that is controlled by vMIA during infection." (PMID 18769594, 2008). "Premature cmvPCD initiated in mutant virus-infected cells prevented comparisons by immunoblot later in infection; however, immunofluorescence analyses at 96 h postinfection confirmed the dramatically increased HtrA2/Omi levels in mutant or wt virus-infected cells." (PMID 18769594, 2008). "Thus, ΔUL37x1-mutant virus-infection preserves mitochondrial networks throughout infection, during HtrA2/Omi accumulation and initiation of premature cmvPCD." (PMID 18769594, 2008). "CMV infects many cell types in addition to HFs, and given that the timing of replication varies with cell type, vMIA control of HtrA2/Omi-dependent death may be critical in other cell types or in natural infection of the human host." (PMID 18769594, 2008). "Further, HtrA2/Omi remains mitochondrial late during infection suggesting death may be initiated by the activity of the intramitochondrial protease, which raises an interesting question as to how transduction of the death signal occurs." (PMID 18769594, 2008). "Introduction of HtrA2/Omi or mutant expression constructs did not influence the antiapoptotic activity of vMIA, consistent with previous work showing vMIA-dependent antiapoptotic function is active at late times of infection." (PMID 18769594, 2008).